GDF15 (growth differentiation factor 15)
Diseases named in the same sentence as GDF15 in open-access papers (continued):
Sharing a sentence is not in itself a finding about the gene and the disease.
cancer (continued). "For participants in the cancer group with both pre-treatment baseline levels and 3-month treatment levels, there was no statistical difference in GDF15 between time points (p=0.702)." (PMID 38146512, 2023). "GDF15 was elevated in children with cancer at diagnosis compared to controls but did not correlate with anthropometric measurements or QOL." (PMID 38146512, 2023). "Much attention has been paid to the roles of GDF15 and FGF21 in cancers." (PMID 36642986, 2023). "Growth differentiation factor 15 (GDF‐15) is a TGF‐β superfamily cytokine that responds to mitochondrial stress, tissue damage, and hypoxia, and is a strong predictor of disease severity in inflammation, cancer, and infection." (PMID 35923762, 2022). "These indicates that CHOP-induced GDF-15 and TRIB3 have significant roles in cancer." (PMID 36008442, 2022). "For example, tumor-derived GDF-15 suppresses the proapoptotic activity through inhibiting TGF-β-activated kinase (TAK1) signaling to nuclear factor-κB, thereby evading macrophage-mediated immune surveillance and stimulating early cancer development." (PMID 35508696, 2022). "Finally, two other monoclonal antibodies against GDF15, AV-380 and CTL-002, are currently under investigation in Phase I trials in healthy subjects and cancer patients, respectively." (PMID 36078078, 2022). "Our results concerning density and characterization of GDF-15+ MΦ extend data of others showing that GDF-15/MIC-1 mRNA expression—detected by in situ hybridization—only exists in carcinoma, but not in benign tissue." (PMID 36230513, 2022). "Besides, transcriptome RNA sequencing (RNA-Seq) was performed to explore the cancer-promoting effects of NR5A2, we found that GDF15 is a component of multiple down-regulated tumor-promoting gene sets after NR5A2 was silenced." (PMID 33850096, 2021). "More recent observations support a model in which supernumerary centrosomes in cancer cells can promote the overproduction and secretion of cytokines and pro-invasive factors, such as IL-8, ANGPTL4 (Angiopoietin Like 4), and GDF-15 (Growth Differentiation Factor 15)." (PMID 33922633, 2021). "Despite the breakthrough in inhibiting the GDF15/GFRAL pathway for the treatment of cachexia in the mouse model, several issues concerning interplay between host and tumor must be addressed for cachectic cancer patients." (PMID 33442410, 2021). "Important genes that impact cancer, such as CD70, JAK3 and GDF15, are found on ch19." (PMID 34063545, 2021). "Higher levels of GDF-15 may be useful for the diagnosis and management of CVD and cancer and are a strong predictor of mortality from either disease." (PMID 34150865, 2021). "The GDF15/GFRAL pathway is known to affect energy homeostasis, which could have implications for cancer initiation and progression." (PMID 33086658, 2020). "Both TGFβ1 and GDF15 belongs to TGF-β superfamily, TGFβ1 was reported to activate SREBP2 in kidney mesangial cells, SREBF2 activation was dependent on SCAP, SCAP or SREBPs promoted tumor progression in various cancer." (PMID 33123476, 2020). "On the contrary, our study failed to establish a relation between GDF-15 and cancer-related mortality, in spite of the fact that this relation has been described in the literature." (PMID 33419237, 2020). "A growing number of studies implicates that increased GDF15 could promote mitochondrial fat acid β-oxidation (FAO), which is essential for metastasis of cancer cells." (PMID 32076610, 2020). "We demonstrate that GFRAL cells are a sub-population of CCK neurons, which respond to administration of GDF15 or the cancer therapeutic drug, cisplatin, but not to other anorectic signals." (PMID 32723474, 2020). "The inhibition of GDF15 activity, by targeting its receptor GDNF family receptor alpha-like (GFRAL) in brainstem neurons of tumor-bearing mice, identified a novel strategy for cancer cachexia treatment." (PMID 33374852, 2020).
cancer (continued). "GDF15, a member of transforming growth factor β (TGF-β)/bone morphogenetic protein (BMP) superfamily, is expressed in many types of tissues and has gained extensive attention with the increase in research on cancer progression." (PMID 33062674, 2020). "The production of TGFβ, leukaemia inhibitory factor (LIF), growth arrest-specific protein 6 (GAS6), fibroblast growth factor 5 (FGF5), growth differentiation factor 15 (GDF15) and hepatocyte growth factor (HGF) promotes invasive and proliferative behaviour in cancer cells." (PMID 31980749, 2020). "It would thus be surprising if GDF-15/GFRAL/RET inhibitors were not simultaneously developed for the treatment of cancer." (PMID 32508832, 2020). "Previously, the topic of whether GDF-15 could serve as prognostic markers for OS, DFS, or RFS in cancer was considered controversial." (PMID 30808336, 2019). "Nevertheless, we intended to investigate the alterations of GDF‐15 as a general phenomenon in cancer, without focusing on distinct tumour entities." (PMID 31463975, 2019). "A correlation analysis of hepcidin/GDF15 and hemoglobin levels revealed that hepcidin and GDF15 correlated with hemoglobin levels in cancer patients, but not in controls." (PMID 30646851, 2019). "From a cardio‐oncologic perspective, there are currently no data regarding the relationship between dysregulation of GDF‐15 and other cardiac biomarkers in cancer patients available." (PMID 31463975, 2019). "Since the role of GDF15 in cancer progression is controversial and not fully elucidated yet, we first tested GDF15 expression in three cell lines H4, SW1088, and A172 both at the mRNA and protein level." (PMID 31412547, 2019). "Moreover, our knowledge of the molecular mechanism in which GDF15 and RSU-1 are involved will facilitate the identification of therapeutic targets in signaling pathways that are crucial to cancer development and progression." (PMID 31412547, 2019). "Interestingly, two cancer-related genes, NAG-1 (officially known as GDF15), and thymosin β-4 (TMSB4X), were induced by SC-560, thus suggesting potentially contrasting effects on its antitumor activity." (PMID 30314310, 2018). "In agreement with the role of FGFR1 in promoting cell proliferation and carcinogenesis, a number of iFGFR1-upregulated genes are cancer-driving genes such as ETS1, PIM1, NRG1, MMP1, and FOXQ1, while some iFGFR1-downregulated genes are tumor suppressors such as NR4A1 and GDF15." (PMID 30111373, 2018). "In this study, we hypothesize that GDF15 maintains cancer stem-like cells in an autocrine/paracrine manner; GDF15-activated ERK1/2 seems to induce GDF15 at transcription levels, resulting in continuous production of GDF15 protein." (PMID 28206960, 2017). "To analyze cancer cells where the GDF15 autocrine/paracrine circuits are potentially active, even in the absence of exogenous GDF15 stimulation, we first examined expression of GDF15 in MCF7 cells by immunocytochemistry." (PMID 28206960, 2017). "It is possible that a large amount of exogenous GDF15 triggers formation of the GDF15 circuits in cancer cells where GDF15 circuits are not active." (PMID 28206960, 2017). "GDF15 is a divergent member of the transforming growth factor-beta (TGF-β) superfamily that exerts complex effects on several cellular pathophysiology conditions including stress responses, bone formation, ischemia, and cancers." (PMID 29262584, 2017). "In conclusion, this study revealed that GDF15 may be a novel functional secreted molecule for DGC progression, possibly having important roles for cancer progression via the affecting fibroblast function, as well as TGF-β." (PMID 26892343, 2016).
cancer (continued). "Growth-differentiation factor 15 (GDF 15) is a member of the transforming growth factor-b (TGF-b) superfamily, involved in tumor pathogenesis and its expression is increased in many types of cancers." (PMID 27034760, 2016). "There are no other data from transgenic cancer models where the effect of MIC-1/GDF15 on advanced cancers has been investigated." (PMID 25695521, 2015). "In patients with advanced cancers, serum MIC-1/GDF15 levels commonly rise from a normal mean of about 450pg/ml to 10,000–100,000 pg/ml or more and may cause cancer anorexia/cachexia." (PMID 25695521, 2015). "Lapatinib treatment suppressed GDF15-mediated HER2 phosphorylation, suggesting that lapatinib may remain effective in cancers that are resistant to trastuzumab due to upregulation of GDF15." (PMID 23227361, 2012). "Importantly, circulating GDF-15 levels are strongly influenced by non-disease factors such as age, smoking, cancer, and exposure to medications including metformin and chemotherapy." (PMID 41157213, 2025). "Importantly, this molecule is found to be upregulated in the circulatory system of both early (I/II) and late (III/IV) stage patients, suggesting that the increase in GDF-15 is not secondary to cancer progression." (PMID 39989973, 2025). "Importantly, the lack of association between GDF-15 and VTE underscores its specificity and potential utility as an optimal biomarker for bleeding risk prediction in cancer patients." (PMID 39967200, 2025). "With the exception of cancer and diabetic diagnoses, we were limited by having had no information on other factors/conditions that could influence GDF15 levels in plasma e.g., smoking and medications." (PMID 40562759, 2025). "While GDF-15 correlates with multiple epigenetic clocks, its specificity remains questionable due to its elevation in diverse non-age-related acute stress states including cancer, CVD, and renal disease." (PMID 41281356, 2025). "This extensive research suggests that increased GDF-15 levels in cancer cachexia may not just result from the condition but could also play a causative role in its development." (PMID 41294666, 2025). "Unfortunately, study of GDF15 in paediatric oncology is mostly limited to the long‐term cardiotoxicity in childhood cancer survivors who received anthracycline therapy without dedicated disease‐specific study of GDF15's role in development, progression, or treatment resistance." (PMID 40019842, 2025). "Recent advancements in understanding the pathophysiology of cancer cachexia have identified potential therapeutic targets, including tumor-derived mediators such as leukemia inhibitory factor (LIF), zinc alpha glycoprotein (ZAG), activin A, and growth differentiation factor 15 (GDF-15)." (PMID 39727925, 2024). "Interestingly, GDF-15 was found to exert immune-regulatory functions in cancer and noncancer pathologic conditions." (PMID 39283723, 2024). "In contrast, DOX-untreated cancer cells showed no notable “blocks” of co-expression patterns for the analyzed genes, despite the presence of correlation between single marker genes such as the senescence markers GDF15 and CDKN1A." (PMID 39405604, 2024). "Furthermore, GDF15 induced apoptosis in some cancer cells, including A549 and HCT-15, but not others." (PMID 38213743, 2024). "Lastly, the endpoint of all-cause mortality rather than cause-specific mortality could have influenced the results as for example GDF-15 is a biomarker seen in a broad range of (inflammatory) disease (processes) and not solely bound to cancer and/or HF." (PMID 39103886, 2024). "Secondly, how GDF15 regulate various hallmarks of cancer is not clear." (PMID 38230211, 2024). "GDF-15 is a pleiotropic cytokine of emerging interest in cancer, and we saw that GDF15 transcript levels in CT26 tumors were markedly elevated by 5FU+OHP containing treatments; mirroring findings from other mouse models and human cancer patients on platinum therapy." (PMID 38206570, 2024).
cancer (continued). "Therefore, it is not surprising that cancer cachexia patients experience an upregulation of GDF-15, and exciting advances have been made to inhibit the GDF15-GFRAL axis." (PMID 38254849, 2024). "Therefore, strategies targeting the GDF15-GFRAL-RET axis might be of interest to dogs with PPGL, both by their direct anti-tumor effect and by reducing cancer cachexia." (PMID 37691636, 2023). "In addition to integrins, we identified other glycoproteins regulated by B4GALT1, such as neutral amino acid transporter (SLC1A5), insulin receptor (INSR), and growth/differentiation factor 15 (GDF15), which have been reported to modulate cancer malignant phenotypes." (PMID 37907465, 2023). "Circulating GDF15 and IL6, derived from cancer cells, could perhaps activate brown fats." (PMID 37886942, 2023). "Second, the primary objective of the study was to detect a difference in GDF15 between participants with cancer compared and a control group, but it was not powered to find potential small differences in anthropometrics or QOL measures, and we had small number of participants." (PMID 38146512, 2023). "How GDF15 induces the radioresistance of cancer cells is not well understood." (PMID 38201456, 2023). "No studies have examined GDF15 in children with newly diagnosed cancer." (PMID 38146512, 2023). "However, the role of GDF15 in cancer progression has not been elucidated as its expression levels vary among patients and cancer types." (PMID 35280749, 2022). "In this context, a divergent member of the TGF-beta superfamily, i.e., growth differentiation factor-15 (GDF-15)—also known as MΦ inhibitory cytokine-1 (MIC-1), NSAID-activated gene-1, placental bone morphogenetic protein (PLAB) —is overexpressed by a majority of cancers." (PMID 36230513, 2022). "Notably, GDF15 may also contribute to common manifestations of cancer, such as anorexia and CRA, leading to a poorer overall prognosis in cancer patients." (PMID 35694408, 2022). "Compared with the previous reports, our study not only confirmed the role of GDF-15 in cancer cachexia but also showed that GDF-15 could be secreted by tumor cells into tumor-derived exosomes and contributed to the high circulation level of GDF15 in cancer cachexia animals." (PMID 35379793, 2022). "CAFs directly stimulate cancer cell growth and also enhance tumor angiogenesis by paracrine signaling, such as vascular endothelial growth factor (VEGF), hepatocyte growth factor (HGF), growth differentiation factor 15 (GDF15), C-X-C Motif Chemokine Ligand 12 (CXCL12) and CXCL14." (PMID 34681633, 2021). "This suggests that while increased GDF‐15 expression may be a harbinger of prostate cancer development, overexpression of GDF‐15 may also serve a tumor suppressive function in terms of limiting the spread of cancer." (PMID 33784024, 2021). "Third, the study outcomes were cancer and CVD mortality, so we could not assess the prognostic value of GDF-15 for the development of cancer and CVD in this study." (PMID 34150865, 2021). "Moreover, the production of TGFβ, leukemia inhibitory factor (LIF), growth arrest-specific protein 6 (GAS6), fibroblast growth factor 5 (FGF5), growth differentiation factor 15 (GDF15), and hepatocyte growth factor (HGF) promotes invasive and proliferative behavior in cancer cells." (PMID 34646829, 2021). "GDF15, a divergent member of the transforming growth factor β superfamily, is an emerging biomarker comparable to FGF21, as its circulating levels are noticeably increased in various disease conditions including cancer, metabolic diseases, and aging-related disorders, as well as MetS." (PMID 33668309, 2021). "On the other hand, it has been reported that GDF-15 exerts a cardioprotective effect through the activation of anaplastic lymphoma kinase (ALK) receptors and phosphorylation of the Smad signaling pathway and that it has an overall protective role in early cancer." (PMID 34150865, 2021).
cancer (continued). "While these findings were specific to the cancer cachexia setting, they suggest that there may be mechanistic differentiation to a GDF15-based therapeutic unlike classic anorectic agents such as GLP-1." (PMID 33903632, 2021). "Other cancer progression-related genes that became differently expressed in PNX0010 cells under PARG overexpression are serpin family E member 1 (SERPINE1), colony-stimulating factor 2 (CSF2 or GM-CSF), ubiquitin specific peptidase 10 (USP10), and growth differentiation factor 15 (GDF15)." (PMID 34638458, 2021). "Serum GDF-15 levels might be elevated in patients with CVD and cancer compensatorily." (PMID 34150865, 2021). "Thus, it is unclear whether GFRAL inhibitors, which are being developed and tested to treat cancer anorexia (clinical trial identifier NCT04068896), could be a valid alternative to anti-GDF-15 antibodies for immunotherapy." (PMID 32508832, 2020). "Moreover, among all cancer patients, we observed a negative correlation between GDF-15 serum levels and FAACT score (r = −0.280, p = 0.03)." (PMID 33396237, 2020). "Thus, in vitro and in vivo studies suggest that the effects of GDF-15 on cancer cells are manifold, even when no GFRAL-expressing neuronal cells are present." (PMID 32508832, 2020). "Although not so extensively studied, GDF-15 may be related to cancer diagnosis and tumor progression." (PMID 33419237, 2020). "During cancer, GDF-15 could activate these “non-homeostatic” pathways–specifically acting on the GFRAL-expressing neurons localized in the area postrema and nucleus of the solitary tract—which are able to regulate body weight." (PMID 33396237, 2020). "Distinct from the extracellular effect of CALU-1/− 2 in downregulated cancers, CALU-15 facilitated the nuclear expression of nucleus GDF-15, which then mainly promoted cell migration and tumour metastasis; our study confirmed that CALU promoted the expression of GDF-15." (PMID 31118065, 2019). "Also, given the association that high plasma level of GDF-15 decreases time to recurrence, further emphasizes that GDF-15 is increased due to the patient’s cancer status as reduced time to recurrence is not likely to be influenced by cardiovascular disease." (PMID 30645608, 2019). "In our stratified analysis, 4 groups of carcinomas had been evaluated repeatedly: the pooled AUC of GDF-15 to rule out PC, EC, GC, and HCC were estimated to be 0.82, 0.84, 0.90, and 0.85, respectively, showing that GDF-15 testing achieved a significant level of efficacy in confirming GC." (PMID 30808336, 2019). "Growth differentiation factor-15 (GDF-15), also known as macrophage inhibitory cytokine-1 (MIC-1), is a member of the transforming growth factor (TGF-ß) cytokine superfamily, which has been examined as a novel emerging biomarker in HF, cancer and atherosclerotic diseases including CVD." (PMID 29771963, 2018). "The lack of association between GDF-15 at baseline and a cancer diagnosis at baseline the ULSAM cohort are probably related to that these diagnoses relate to previously successfully treated cancer disease." (PMID 24312445, 2013). "Therefore, elevation of GDF-15 level might be a reason for further investigations and/or strengthen the indication for preventive measures against both CVD and cancer." (PMID 24312445, 2013). "Consequently, circulating GDF15 levels rise under ‘non-homeostatic’ conditions of adiposity, starvation, mitochondrial dysfunction, and insulin resistance, but also in inflammatory diseases and various cancer types." (PMID 38474863, 2024). "Interestingly, nonsteroidal anti-inflammatory drugs increase GDF-15 expression in cancer cells." (PMID 36361969, 2022).